IQCF3 (IQ motif containing F3)
Tractability: No criterion of Open Targets' tractability assessment is met for any kind of drug.
Gene: Protein-coding gene on chromosome 3 (51,826,883 to 51,833,389, forward strand). Ensembl gene ENSG00000229972.
Subcellular location (Human Protein Atlas): Nucleoli
Gene Ontology:
Molecular function: protein binding; calmodulin binding
Genetic constraint (gnomAD): Loss-of-function variants: 7 observed, 5.89 expected, observed/expected ratio (o/e) 1.19, 90% interval 0.66 to 1.86. That is too few expected variants to judge how well the gene tolerates losing a copy. Missense variants: 189 observed, 201.48 expected, observed/expected ratio (o/e) 0.94, 90% interval 0.83 to 1.06. Synonymous variants: 82 observed, 76.02 expected, observed/expected ratio (o/e) 1.08, 90% interval 0.9 to 1.3.
Homologues: Orthologues: chimpanzee IQCF3 (100% identical), macaque IQCF3 (93% identical), pig IQCF3 (64% identical), dog IQCF3 (62% identical), rabbit IQCF3 (61% identical), mouse Iqcf3 (52% identical). Paralogues in human: IQCF2 (42% identical), IQCF6 (38% identical), IQCF5 (37% identical), IQCF1 (35% identical).
Diseases named in the same sentence as IQCF3 in open-access papers:
IQCF3 is named in the same sentence as 2 diseases in open-access papers, as found by Europe PMC text mining. Sharing a sentence is not in itself a finding about the gene and the disease.
IQCF3 shares sentences with these, for which no sentence is quoted: metastatic melanoma (1 paper); metastatic tumors (1).